IL6 (interleukin 6)
Diseases named in the same sentence as IL6 in open-access papers (continued):
Sharing a sentence is not in itself a finding about the gene and the disease.
emphysema (continued). "IL-6 is consistently elevated in systemic circulation of patients with emphysema and COPD." (PMID 32280354, 2020). "Analysis in mice revealed that development of emphysema was reliant on IL-6." (PMID 31694340, 2019). "Treatment of wt mice with cigarette smoke increased emphysema-associated lung volume increase, which was not seen in IL-6-deficient animals." (PMID 31694340, 2019). "While this study was unique in that it featured two large well-characterized cohorts, confirmed strong associations of IL-6 and eotaxin, identified new pQTL SNPs, and identified potentially new biomarkers of COPD and emphysema progression, there were some important limitations." (PMID 29065892, 2017). "Recent experimental evidence in mouse models supports the involvement of IL-6 trans-signaling in the development of emphysema via activation of the mammalian target of rapamycin complex 1 (mTORC1) pathway and that this is independent of the inflammatory response." (PMID 28334838, 2017). "Importantly, CC sensitivity appears to be a stronger predictor of PWV than previously reported associations comparing arterial stiffness with FEV1 (r2 = 0.11), IL-6 (r2 = 0.09) and emphysema severity (r2 = 0.22)." (PMID 27355356, 2016). "The previous studies reported that both CS and LPS directly damaged airway epithelium and activated macrophages and lymphocytes to generate proinflammatory cytokines (such as TNF-α, IL-6, IL-8, and IL-1β), which then activated neutrophils, leading to chronic bronchial inflammation and emphysema." (PMID 27524867, 2016). "In the present study, the decreased SOD concentration and increased IL-6 concentration in the serum were confirmed in the emphysema models whether induced by CS exposure or intraperitoneal injection of CSE." (PMID 25814921, 2015). "Within the IL-6 cytokine family, only IL-6 was significantly up-regulated in the lungs of gp130F/F mice, and the genetic targeting of IL-6 in gp130F/F mice (gp130F/F:IL-6−/−) prevented emphysema." (PMID 24144354, 2014). "In a cross-sectional study we validated that T cell responses to two cytokines, IFN-γ and IL-6 and a newly developed dual cytokine assay (γ-6 Spot), could discriminate emphysema with 90% sensitivity." (PMID 22969766, 2012). "Consistently, in this much larger cohort using a CD4+ T cells to APCs ratio (10:1), we found a strong positive correlation between the production of IFN-γ (r = 0.59, P < 0.0001) and IL-6 (r = 0.58, P < 0.0001), and the severity of emphysema as determined by quantitative CT scan." (PMID 22969766, 2012). "Second, elastase-induced emphysema can be modulated by different conditions (i.e. IL-6 or Nrf2 knocking down), showing that it’s a dynamic process, susceptible to be modulated by exposure to NPs, which does not result only from initial tissue destruction by exogenous elastase." (PMID 22849372, 2012). "Levels of proinflammatory cytokines (TNF-α and IL-6) that may mediate muscle wasting, although low, were significantly increased in the limb muscle of tumor-bearing animals without underlying emphysema (U group)." (PMID 27549759, 2016). "Thus, production of IL-6 and IL-17 in response to lung antigen is seen in ever-smokers with emphysema, but IFN-γ is produced most consistently in those with both airflow obstruction and emphysema, possibly because these smokers tend to have more severe disease." (PMID 22969766, 2012). "The striking sensitivity of the association between IFN-γ and/or IL-6 responses in T cells stimulated with EFs and emphysema prompted us to develop a PBMC-based assay that could be used as a screening tool to discriminate emphysema in the same cohort." (PMID 22969766, 2012). "Meanwhile, compared to patients with emphysema and normal lungs, patients with CPFE had higher levels of serum inflammation, characterized by significantly elevated levels of WBC, CRP, IL-6, and fibrinogen." (PMID 40507634, 2025).
emphysema (continued). "Compared to the emphysema model (ELA), the ACO group was superior in expressing of IL-1β, IL-4, IL-5, IL-6, IL-13, and IFN-γ." (PMID 37511021, 2023). "The IL-6 and IFN-γ levels in the BALF and serum were lower in the high-pectin diet group than those in the emphysema group." (PMID 33772084, 2021). "IL-6 and IFN-γ cytokine levels in the BALF and serum decreased in emphysema mice receiving SCFAs compared with emphysema mice." (PMID 32681029, 2020). "Concerning pulmonary inflammation, it was observed that IL-6 directly activates STAT3, while in pulmonary emphysema, IL-6 drives the activation of STAT3 in a different manner." (PMID 29326759, 2017). "PPE instillation in mice is a useful model to reproduce quickly several features of human emphysema and PPE instillation increased macrophages as well as IL-6, KC, IL-1β and IL-17 levels in BALF." (PMID 27775634, 2016). "The presence of macrophages is the main factor involved in emphysema because they release inflammatory mediators such as TNF-α, IL-6, and MMPs at the injury site." (PMID 26646821, 2015). "The areas under the receiver operating characteristic curve to predict emphysema for interferon gamma (IFN-γ), and interleukin 6 (IL-6) responses to EFs were 0.81 (95% CI of 0.74–0.88) and 0.79 (95% CI of 0.72–0.86) respectively." (PMID 22969766, 2012). "At day 3 post infection, treatment with IL-6, IL-13, and IFN-γ provoked mild PE and severe emphysema that were accompanied by pulmonary dysfunction in EV71-infected, but not herpes simplex virus-1 (HSV-1)-infected control mice." (PMID 22054060, 2011). "iNOS, an enzyme involved in the macrophage inflammatory response and upregulated by hypoxia or proinflammatory cytokines, such as tumor necrosis factor-α (TNF-α), interleukin 6 (IL-6), or interferon-γ (IFN-γ), plays a crucial role in the development of tobacco smoke–induced emphysema and PH in mice." (PMID 37581311, 2023). "Some scholars have confirmed that cytokines, mainly IL-6 secreted by macrophages, have strong neutrophil chemotaxis and have been confirmed to be related to the severity of COPD, the rate of decline in lung function, and the progression of emphysema." (PMID 37400851, 2023). "PLWH with emphysema had higher concentrations of TNFα (median (IQR): 8.2 (6.4-9.8) versus 7.1 (5.7-8.6) pg/ml, p<0.001), IL-1β (0.21 (0.1-0.4) versus 0.17 (0.1-0.3) pg/ml, p=0.004) and IL-6 (3.6 (2.6-4.9) versus 3.1 (2.0-4.3) pg/ml, p=0.023) than PLWH without." (PMID 33936110, 2021). "Salidroside treatment decreased emphysema, significantly ameliorated lung function, increased antioxidant, but reduced MDA, IL-6 and TNF-α levels in serum and GN tissues of rats, accompanied by decreased myostain, but increased myogenin expression in GN tissues." (PMID 31702007, 2019). "The morphological changes were also accompanied by an increase in lung lymphocytes, macrophages, macrophage-derived metalloproteases, neutrophils, neutrophil elastase, oxidants, IL-6, and TNF-α, all of which have been demonstrated to play significant roles in the pathogenesis of emphysema." (PMID 28737721, 2017). "Meanwhile, the decreased SOD concentration and increased IL-6 concentration in the serum could be observed in both CS exposure-induced emphysema and intraperitoneal injection of CSE-induced emphysema." (PMID 25814921, 2015). "We next examined the number of individuals with or without emphysema with more than a 1.5-fold increase in cytokine, and found that the highest sensitivity (91%) corresponded to either a positive IL-6 or IFN-γ response." (PMID 22969766, 2012). "The levels of IL-6 and IFN-γ in bronchoalveolar lavage fluid (BALF) were lowest in the high-fiber diet group, and the local concentration of SCFAs was markedly higher in mice with emphysema following fecal microbiota transplantation and the high-fiber diet than in mice with emphysema." (PMID 35563159, 2022).
emphysema (continued). "Although the study was focused on airway inflammation, not emphysema, considering that IL-6 and its signaling play a main function in emphysema pathogenesis, we could expect association of NNMT and emphysema through IL-633." (PMID 34404834, 2021). "PLWH with emphysema had higher concentrations of TNFα, IL-1β and IL-6 than PLWH without emphysema." (PMID 33936110, 2021). "The proinflammatory cytokines IL-6 and TNFα have been reported to increase, following exposure to cigarette smoke and WPS, and to play a significant role in the acute smoke-induced inflammatory reaction in the lung, occasioning connective tissue damage which ultimately leads to emphysema." (PMID 32025277, 2020). "Elastase injection was performed to induce mouse emphysema, and these mice were treated with a specific AMPK activator metformin as well as Compound C. AICAR reduced, whereas Compound C increased CSE-induced increase in IL-8 and IL-6 release and expression of genes involved in cellular senescence." (PMID 28186975, 2017). "Freshly isolated CD4+T cells from PBMC of ever-smokers without (controls; n = 61) or with emphysema (n = 95) that were stimulated with lung EFs showed specific induction of IL-6, IL-17A, and IFN-γ in emphysema (right three scatter plots) as compared to controls." (PMID 22969766, 2012). "In addition, there were increased mRNA levels of TNF‐α, IL‐6, GCSF, macrophage inflammatory protein‐2 (MIP‐2), KC, and protein expression of nuclear factor kappa‐light‐chain‐enhancer of activated B cells (NF‐κB) in lung tissue and the destruction of airway spaces (a feature of emphysema)." (PMID 37119028, 2023). "Furthermore, RLD significantly inhibited the expressions of IL‐1β, IL‐6, TNF‐α, and TGF‐β induced by cigarette smoke exposure, reduced the number of inflammatory cells in the bronchoalveolar lavage fluid, and alleviated the severity of cigarette smoke‐induced emphysema." (PMID 28749079, 2017). "In the COPDGene cohort, there was a significant association with 5-year decline in FEV1 and IL-6 in subjects who did not have COPD or emphysema and significant association with 5-year decline in FEV1 and IL-8 in subjects who had chronic bronchitis, but no emphysema." (PMID 29065892, 2017). "Notably, IFN- γ and IL-6 secretion in response to EFs did not significantly change in the control group, indicating that increases in EF-specific T cell cytokine secretion persist in ever-smokers with emphysema." (PMID 22969766, 2012). "PLWH with emphysema had higher concentrations of TNFα (median (IQR): 8.2 (6.4-9.8) versus 7.1 (5.7-8.6) pg/ml, p<0.001), IL-1β (median (IQR): 0.21 (0.1-0.4) versus 0.17 (0.1-0.3) pg/ml, p=0.004) and IL-6 (median (IQR): 3.6 (2.6-4.9) versus 3.1 (2.0-4.3) pg/ml, p=0.023) than PLWH without emphysema." (PMID 33936110, 2021). "IL-6 was significantly higher in smokers with emphysema than in the other two groups while TNF values were similar in all groups, and CRP tended to be higher in smokers with or without emphysema (ANOVA, p = 0.077)." (PMID 17822550, 2007). "To test this hypothesis, we measured serum interleukine-6 (IL-6), tumor-necrosis factor (TNF), and C-reactive protein (CRP) in smokers with emphysema, smokers without emphysema, and in non smokers with normal lung function." (PMID 17822550, 2007).
head and neck cancer (89 papers, 1992 to 2025). A primary or metastatic malignant neoplasm affecting the head and neck. "In particular, recent studies have reported that IL-6 is associated with the effects of immune checkpoint inhibitor in the treatment of head and neck cancer." (PMID 35089951, 2022). "Many studies have reported a high concentration of IL-6 in the serum of patients with head and neck cancer and have associated high IL-6 levels with a poor prognosis." (PMID 27073100, 2017). "A previous study that detected salivary cytokines in patients with head and neck cancer with concurrent CTx and RT reported a significant increase in the salivary levels of IL-1β, IL-6, and TNF, that were all positively associated with the mucosal toxicity severity." (PMID 35476641, 2022). "Clinically, IL-6 has also been found to be over-expressed in almost all types of tumors and is associated with a poor prognosis of cancers such as cervical, lung, gallbladder, and head-neck cancers." (PMID 30642292, 2019). "However, the association between the increased IL-6 expression and clinical prognosis for head and neck cancer patients remains controversial." (PMID 25761055, 2015). "However, the association between increased IL6 expression and clinical prognosis for head and neck cancer patients remains controversial." (PMID 23185547, 2012). "Post-translational regulation of TWIST1 might also be mediated through mutated EGFR activation, indeed, in head and neck cancer, IL6 activation was recently shown to stabilize TWIST1 through CK2 phosphorylation." (PMID 22272264, 2012). "There is only one study comparing salivary IL‐6 in head and neck cancer patients before and after surgical treatment, which supports the results of this study outcome." (PMID 40831233, 2025). "Specific combinations of keywords were used: (“salivary cytokines” OR “salivary interleukin 6” OR “salivary interleukin 8” OR “salivary epidermal growth factor”) AND (“head and neck cancer”) AND (“radiotherapy”)." (PMID 41220465, 2025). "We delve into the potential mechanisms by which NAT facilitate cervical lymph node metastasis in head and neck cancer, particularly through the secretion of adipokines such as leptin, adiponectin, and Interleukin-6." (PMID 38800384, 2024). "In cancer, including head and neck cancer (HNC), certain key players in the body’s inflammatory process, such as the interleukin (IL)-6 and IL-1 systems, are associated with outcomes." (PMID 38672565, 2024). "IL-6 is one of the major chemokines present in the serum of patients with head and neck cancer, and elevated IL-6 levels have been reported to independently predict tumor recurrence, decreased survival, and tumor metastasis." (PMID 39126553, 2024). "There are several ways that MSCs can promote drug resistance in cancer cells, mostly through the secretion of cytokines like IL-6, IL-7, and IL-8, for example, in head and neck carcinomas, where these molecules induce paclitaxel resistance." (PMID 38674102, 2024). "The cytokine that was most highly correlated with fatigue and neuropsychological measures at baseline in the cervical and head and neck cancer patients in this study was IL-6." (PMID 36354718, 2022). "Serum levels of IL-6 were increased following radiation or chemo-radiation therapy in head and neck cancer." (PMID 36387244, 2022). "The aim of this article is to elucidate the role of IL-6 in the tumor ecosystem and to review the possible therapeutic approaches in head and neck cancer." (PMID 34681685, 2021). "Suppression of CD147 diminishing IL-1β, IL-6, and IL-8 production was previously demonstrated in head and neck cancer." (PMID 34948304, 2021). "IL-6 is one of the main chemokines present in serum samples of head and neck cancer patients and elevated IL-6 levels independently predict tumor recurrence, poor survival and tumor metastasis." (PMID 31297730, 2019). "In this study we analysed the effect of EMC, especially mediated through IL-6 in head and neck cancer cells." (PMID 31297730, 2019).
head and neck cancer (continued). "An increase of IL-6 has earlier been shown in 15 patients with head and neck cancer by examining repeated blood samples up to end of chemoradiotherapy which is in agreement with the findings in the present study." (PMID 31750257, 2019). "In head and neck cancer, IL-6 can induce its expression as upstream of OPN, and OPN promotes the growth, migration and invasion of cancer cells through activating integrin αvβ3-NF-kappa B axis." (PMID 30175384, 2018). "Circulating interleukin-6 (IL-6) improves outcome prediction for second primary cancer (SPC) in head and neck cancer (HNC) patients." (PMID 29951282, 2018). "We next tested the efficacy of combination treatment in a naturally high IL-6 expressing head and neck cancer cell line (UM-SCC-74A)." (PMID 28978005, 2017). "In head and neck cancers, IL-6 expression and its role in STAT3 activation and tumor growth has been extensively documented." (PMID 28978005, 2017). "Here, we evaluated the significance of endothelial cell-secreted IL-6 on head and neck cancer stem cell motility and the therapeutic potential of targeting IL-6 pathway in HNSCC." (PMID 29245982, 2017). "Our results suggest that BZA inhibits head and neck cancer cell proliferation by blocking IL-6 signaling." (PMID 28978005, 2017). "A number of studies have shown that IL-6 promotes head and neck cancer cell proliferation, migration, survival, invasion, epithelial to mesenchymal transition (EMT), stem cell expansion, and chemoresistance via the activation of JAK/STAT3 signaling pathway." (PMID 28107179, 2017). "In our mechanistic experiments, IL-6 treatment markedly enhanced nuclear translocation of PRMT5 in head and neck cancer cells." (PMID 28107179, 2017). "In conclusion, we demonstrated here the impact of endothelial cell-initiated IL-6 signaling to the migratory phenotype of head and neck cancer stem cells, which are the primary mediators of HNSCC tumor dissemination." (PMID 29245982, 2017). "We had recently shown that IL-6 overexpression promotes tumor metastasis in head and neck cancer by inducing epithelial-mesenchymal transition (EMT)." (PMID 28107179, 2017). "In this study, we demonstrate for the first time that bazedoxifene inhibits head and neck cancer growth and metastasis by blocking IL-6 signaling." (PMID 28978005, 2017). "Increased IL6 expression is thought to specifically promote tumor progression, angiogenesis, or bone invasion in head and neck cancer patients." (PMID 23185547, 2012). "It has been speculated that inflammation of adipose tissue even in distant parts of the body may play a role in head and neck cancers due to systemic effects such as increased circulating IL-6 levels." (PMID 41271789, 2025). "IL-6 promoted the proliferation of head and neck carcinoma cells in vitro." (PMID 40839565, 2025). "Twist has been determined to be stabilized by IL-6 and IL-6 enhanced tumor cell motility could be demonstrated in head and neck cancer cells through activation of CK2." (PMID 36009534, 2022). "IL-6 is an inflammatory and head and neck cancer-related cytokine." (PMID 33924087, 2021). "Mean value levels (ng/ml) of Interleukin 1-beta (IL-1β), Interleukin 6 (IL-6), and Interleukin 10 (IL-10) before treatment, 7 weeks after the start of treatment, 3 and 12 months after the termination of treatment in patients with head and neck cancer." (PMID 31750257, 2019). "Recent studies have shown that IL-6 is one of the main chemokines present in serum samples of cancer patients and elevated IL-6 level is an independent predictor of tumor recurrence, poor survival and tumor metastasis in a number of malignancies including head and neck cancers." (PMID 28978005, 2017). "Indeed, our mechanistic experiments showed that IL-6 treatment of head and neck cancer cells promote PRMT5 translocation to nucleus." (PMID 28107179, 2017). "We had recently shown that IL-6 overexpression promotes tumor metastasis in head and neck cancer." (PMID 26919244, 2016).